FANCL (FA complementation group L)
Description:
Ubiquitin ligase protein that mediates monoubiquitination of FANCD2 in the presence of UBE2T, a key step in the DNA damage pathway. Also mediates monoubiquitination of FANCI. May stimulate the ubiquitin release from UBE2W. May be required for proper primordial germ cell proliferation in the embryonic stage, whereas it is probably not needed for spermatogonial proliferation after birth.
Synonyms: FAAP43; PHF9; FLJ10335; Pog
Tractability: Small molecule: a structure with a bound ligand is known. PROTAC: UniProt records ubiquitination sites on it; ubiquitination databases record sites on it.
Gene: Protein-coding gene on chromosome 2 (58,159,243 to 58,241,410, reverse strand). Ensembl gene ENSG00000115392.
Subcellular location: Cytoplasm; Nucleus
Subcellular location (Human Protein Atlas): Nuclear bodies; Vesicles
Pathways (Reactome):
DNA Repair: Fanconi Anemia Pathway
Immune System: PKR-mediated signaling
Gene Ontology:
Molecular function: protein binding; ubiquitin protein ligase activity; ubiquitin protein ligase binding; ubiquitin-protein transferase activity
Biological process: DNA damage response; DNA repair; protein monoubiquitination; interstrand cross-link repair; protein ubiquitination
Cellular component: chromatin; Fanconi anaemia nuclear complex; cytoplasm; cytosol; nucleoplasm; nucleus; nuclear envelope
Genetic constraint (gnomAD): Loss-of-function variants: 45 observed, 39.96 expected, observed/expected ratio (o/e) 1.13, 90% interval 0.89 to 1.44. The upper end of that interval is the gene's LOEUF score, 1.44, which puts it in group 5 of 6, group 1 being the genes least tolerant of losing a copy. Missense variants: 403 observed, 360.63 expected, observed/expected ratio (o/e) 1.12, 90% interval 1.03 to 1.21. Synonymous variants: 151 observed, 126.82 expected, observed/expected ratio (o/e) 1.19, 90% interval 1.04 to 1.36.
Gene-disease validity (ClinGen):
ClinGen rates the evidence that FANCL causes each of these diseases.
Fanconi anemia complementation group L (autosomal recessive): Definitive. Any Fanconi anemia in which the cause of the disease is a mutation in the FANCL gene.
Homologues: Orthologues: chimpanzee FANCL (99% identical), macaque FANCL (97% identical), pig FANCL (89% identical), dog FANCL (88% identical), rabbit FANCL (88% identical), rat Fancl (79% identical), mouse Fancl (79% identical), guinea pig FANCL (79% identical), tropical clawed frog fancl (65% identical), zebrafish fancl (58% identical), Drosophila melanogaster Fancl (25% identical).
Diseases named in the same sentence as FANCL in open-access papers:
FANCL is named in the same sentence as 54 diseases in open-access papers, as found by Europe PMC text mining. Sharing a sentence is not in itself a finding about the gene and the disease. The quoted sentences say what the papers report.
Fanconi anemia (42 papers, 2010 to 2025). Fanconi anemia (FA) is a hereditary DNA repair disorder characterized by progressive pancytopenia with bone marrow failure, variable congenital malformations and predisposition to develop hematological or solid tumors. "For example, FANCL has been associated with Fanconi anemia and premature ovarian insufficiency, and EPM2A has been linked to Lafora disease." (PMID 38886689, 2024). "In Meso109F, a FANCL (Fanconi Anemia Complementation Group L) DNA sequence variant of uncertain clinical significance was recognized (c.1096_1099dupATTA; p.T367Nfs; variant allele frequency (VAF) 40.7%)." (PMID 36683050, 2023). "Following a similar theme, monoubiquitylation of UBE2T at K86 (5 amino acids from the catalytic cysteine K91) is suggested to reduce E2 activity linked to the Fanconi anemia DNA repair pathway mediated by the E3 ubiquitin ligase FANCL." (PMID 35926457, 2022). "Located at 2p16.1, the interval contained genes encoding vaccinia-related kinase 2 (VRK2) and Fanconi anaemia, complementation group L (FANCL)." (PMID 25087078, 2014). "Mutations in human FANCL lead to Fanconi Anemia (FA), a disease of bone marrow failure, enormous risks of cancer, and hypogonadism and impaired fertility." (PMID 20661450, 2010). "However, POI-24 has either a homozygous frameshift insertion in the FANCL gene, which is also associated with chromosomal instability and Fanconi anemia." (PMID 33095795, 2020). "A severe allele of human FANCL causes a clinical phenotype that includes hematopoietic and skeletal abnormalities that are similar to, or more severe than, those typically observed in patients suffering from a defect upstream in the Fanconi Anemia pathway (H. Joenje, personal communication)." (PMID 20661450, 2010). "Fanconi anemia (FA) complementation group L (FANCL) is an E3 ubiquitin ligase that participates in the repair of DNA damage." (PMID 37327301, 2023). "Similar to FBXL21 ubiquitinating MYOZ1 and TCAP, another E3 ligase, the FANCL subunit of the FA (Fanconi anemia) core complex, has been shown to monoubiquitinate two interacting proteins, namely FANCD2 and FANCI." (PMID 36574402, 2022). "By this means, we identified two large intragenic deletions in FANCL and FANCA, highlighting the importance of searching for this type of variant when analyzing FA genes in patients with Fanconi anemia." (PMID 32235514, 2020). "Six patients had mutations in FANCA, FANCI, FANCL, FANCM and SLX4 genes, which are involved in Fanconi anemia (FA)." (PMID 28423363, 2017). "An example of an exclusive E3-E2 pair is the catalytic center of the Fanconi Anemia (FA) pathway, FANCL-Ube2T." (PMID 24389026, 2014). "Ube2T and FANCL represent a specific E2-E3 ubiquitin-conjugating enzyme and ubiquitin ligase pair required for the function of the Fanconi anemia DNA repair pathway." (PMID 24389026, 2014). "Using the Fanconi Anemia pathway exclusive E3-E2 pair, FANCL-Ube2T, we report the atomic structure of the FANCL RING-Ube2T complex, revealing a specific and extensive network of additional electrostatic and hydrophobic interactions." (PMID 24389026, 2014). "GGN1 and GGN3 have been shown via yeast-two-hybrid assays to interact with FANCL (Fanconi anemia complementation group L)." (PMID 23451117, 2013). "FANCL (alias POG) is an E3 ligase ubiquitinating enzyme and is a key component of the DNA interstrand crosslink repair complex known as the Fanconi Anemia (FA) pathway." (PMID 23451117, 2013). "A genome-wide comparative analysis identified that the accelerated regions in elephants are enriched in Fanconi anemia (FA) complementation group L (FANCL), a ubiquitin E3 ligase that mediates the monoubiquitylation of FANCD2 as an essential step in the FA pathway." (PMID 40708996, 2025). "Moreover, 14% of the patients included in this study harbored deleterious mutations in Fanconi anemia genes (FANCA, FANCD2, FANCF, FANCG FANCI and FANCL) and in WRN, which have been reported to interact with BRCA1." (PMID 38184614, 2024).
Fanconi anemia (continued). "Of particular interest is a case presenting with a FANCL biallelic LoF variant and a positive diepoxybutane test but lacking a full Fanconi anemia phenotypic spectrum." (PMID 33727708, 2021). "Interestingly, germline mutation rate of members of the Fanconi anaemia family of genes (including BRCA2, PALB2, BRIP1, RAD51C, FANCA, FANCI and FANCL) was 53.4% (31/58) among the patients with germline mutations in our cohort." (PMID 32091409, 2020). "FANCL is an E3 ubiquitin ligase of the Fanconi Anemia (FA) core complex." (PMID 26485759, 2015). "Although the FANCL gene has been associated with Fanconi anemia, no clinical features of Fanconi were found in this patient, and therefore it is unlikely that the FANCL gene might cause ovarian failure." (PMID 33095795, 2020). "To explore the mechanistic connection between RAD18 and transcriptional stress, we investigated the Fanconi Anemia pathway, due to the proposed role of RAD18 in localizing FANCL to chromatin." (PMID 36480547, 2022). "HRR alterations involve Fanconi anemia genes (PALB2, FANCA, FANCL, FANCI, FANCC), core RAD genes (RAD50, RAD51, RAD51B, RAD51C) as well as DNA damage response genes (ATM, ATR, CHEK1, CHEK2)." (PMID 36531003, 2022). "The three Fanconi anemia genes FANCC, FANCF, and FANCL were identified as candidate autophagy factors via whole genome screening." (PMID 33575215, 2020). "Jamsai et al30 proposed that GGN1 played a role in meiotic DSB repair in the testis via its connection with the factors such as FANCL and BRCC36 of Fanconi anaemia (FA) and breast cancer (BRCA) pathways to efficiently repair DNA DSBs." (PMID 30055035, 2018). "The other gene in the region, FANCL, codes for a RING-type E3 ubiquitin ligase of the Fanconi anaemia pathway." (PMID 25087078, 2014). "Ube2W has been shown to be responsible for the mono-ubiquitylation of BRCA1 (breast cancer early-onset 1), Fanconi's anaemia proteins FANCL (Fanconi's anaemia, complementation group L) and FANCD2 (Fanconi's anaemia, complementation group D2) and CHIP." (PMID 23560854, 2013). "POI-24 has no Fanconi anemia features, however, although we were unable to rule out FANCL contribution in the POI phenotype of this patient." (PMID 33095795, 2020). "Additionally, we found 7 monoallelic pathogenic variants (2%, 7/327) in 6 genes (besides BRCA1/2) of the interstrand crosslink DNA repair Fanconi anemia pathway (FANCB, FANCC, FANCF, FANCI, FANCL, FANCM) and 1 in RAD51C, a Fanconi-like phenotype gene." (PMID 30262796, 2018). "In our efforts to understand the molecular basis of treatment response in advanced cervical cancer, besides the BRCA pathway, we also found the fanconi anemia (FA) complementation group, FANCD2, FANCL, FANCM, FANCJ/BRIP1/BACH and FANCI, to be involved in intrinsic resistance to chemo-radiotherapy." (PMID 24708616, 2014). "In addition to FANCL, GGN1 interacted with the critical component of the Fanconi Anemia (FA) pathway FANCD2 and a downstream component of the BRCA pathway, BRCC36." (PMID 23451117, 2013). "Three members of the Fanconi Anemia pathway (FANCB, FANCC, and FANCL) were also down regulated." (PMID 24098381, 2013).
anemia (4 papers, 2013 to 2025). A reduction in the number of red blood cells, the amount of hemoglobin, and/or the volume of packed red blood cells. "Interestingly, we found that 10 of 11 patients with lymphoma and another solid tumor harbored germline mutations in Fanconi anemia complementation group (FANC) genes, including FANCI, FANCA, FANCG, FANCL, FANCD1, FANCF, FANCJ, and FANCS." (PMID 37546421, 2023).
pancreatic cancer (4 papers, 2020 to 2024). "So far, pathogenic mutations in FANCL have been shown to predispose to pancreatic cancer, and FANCL silencing has been linked to chemosensitization in lung cancer." (PMID 36046263, 2020).
bone marrow failure (3 papers, 2010 to 2024). "However, the next-generation sequencing of inherited Bone marrow failure related genes showed FANCL heterozygous mutation (Exon9, c.745C > T, p.H249Y)." (PMID 37327301, 2023).
breast carcinoma (3 papers, 2015 to 2022). "Intriguingly, a recent study aimed at identifying breast cancer susceptibility genes reports a significant occurrence of a splice isoform of FANCL in a cohort of non-BRCA breast cancer patients." (PMID 26149689, 2015).
hereditary cancer (3 papers, 2017 to 2022). Malignant neoplasms occurring in families at a rate greater than that expected by chance and caused by germline mutations in a specific gene. "A prospective cohort of 1021 unrelated cancer cases with clinical suspicion of hereditary cancer was screened for mutations in the following 14 FA genes: FANCA, FANCB, FANCC, FANCD2, FANCE, FANCF, FANCG/XRCC9, FANCI, FANCL/PHF9, FANCM, FANCP/SLX4, FANCQ/ERCC4, FANCR/RAD51 and FANCU/XRCC2." (PMID 32235514, 2020). "The majority of germline alterations were unknown or benign, with the exception of one alteration each in familial cancer genes MUTYH, CHEK2, and FANCL, as well as one germline alteration in ID3." (PMID 36232827, 2022).
acute lymphoblastic leukemia (2 papers, 2016 to 2025). Leukemia with an acute onset, characterized by the presence of lymphoblasts in the bone marrow and the peripheral blood. "FANCC was methylated in 1 of 143 acute myeloid leukemia (AML) cases and 3 of 97 acute lymphoblastic leukemia (ALL) cases, while FANCL was found to be methylated in one ALL sample." (PMID 26967246, 2016). "For instance, high methylation of the FANCF (observed in a leukaemic CHRF-288 cell line), FANCC, and FANCL have been reported in a small portion of primary AML and acute lymphoblastic leukemia (ALL) cases." (PMID 40739565, 2025).
epilepsy (2 papers, 2014 to 2022). A brain disorder characterized by episodes of abnormally increased neuronal discharge resulting in transient episodes of sensory or motor neurological dysfunction, or psychic dysfunction. "FANCL has not been previously implicated in epilepsy or any seizure-related phenotype." (PMID 25087078, 2014).
Ewing sarcoma (2 papers, 2021 to 2025). A small round cell tumor that lacks morphologic, immunohistochemical, and electron microscopic evidence of neuroectodermal differentiation. "In particular, fusion-positive Ewing sarcoma cells (A673 and TC32) exhibit exquisite sensitivity to THZ531, a CDK12/13 inhibitor, resulting in the downregulation of the homologous recombination (HR) and DNA damage checkpoint genes, including BRCA1, ATR, FANCl, and FANCD2." (PMID 40760094, 2025).
melanoma (2 papers, 2007 to 2025). A malignant, usually aggressive tumor composed of atypical, neoplastic melanocytes. "FANCA and FANCL mRNAs were clearly upregulated in E2F1 overexpressed SKMEL-2 melanoma cells, whereas FANCD1 and FANCG mRNAs were unchanged after E2F1 overexpression." (PMID 19936073, 2007). "In addition, databases deposited in NCBI revealed that FANCA, FANCL, and probably FANCC genes were upregulated in E2F1-overexpressed SKMEL-2 melanoma cells." (PMID 19936073, 2007).
schizophrenia (2 papers, 2016 to 2020). A major psychotic disorder characterized by abnormalities in the perception or expression of reality. "More recently, a large-scale GWAS found a genome-wide significant association between the FANCL locus and schizophrenia." (PMID 26798408, 2016).
acute leukemia (1 paper, 2021). A clonal (malignant) hematopoietic disorder with an acute onset, affecting the bone marrow and the peripheral blood. "Moreover, hypermethylation of the FANCL promoter region was also suggested to be associated with sporadic acute leukemia." (PMID 33592582, 2021).
depression (1 paper, 2021). "By contrast, FANCL (P = 4.88 × 10−2) showed a significant upregulation in depression cases compared with controls in GSE101521 dataset." (PMID 34021117, 2021). "Several TWAS significant genes were also dysregulated in brains of depression cases compared with controls (including PCDHA8, FANCL, TMEM161B-AS1, GMPPB, STAU1, NDUFA2, GPX1 and PCDHA7), implying that genetic variants may contribute to depression risk by regulating gene expression." (PMID 34021117, 2021).
esophageal squamous cell carcinoma (1 paper, 2015). Esophageal squamous cell carcinoma (ESCC) is a type of esophageal carcinoma (EC) that can affect any part of the esophagus, but is usually located in the upper or middle third. "Increased risk of esophageal squamous cell carcinoma (ESCC) was reported to be associated with mutations in FANCD2, FANCE, FANCL, and FANCA in patients from an Iranian population." (PMID 26596371, 2015).
head and neck cancer (1 paper, 2023). A primary or metastatic malignant neoplasm affecting the head and neck. "Of note, all but two recommendations for therapies with M3 evidence level, i.e., olaparib for the treatment of a head and neck cancer with FANCL mutation and ponatinib for the treatment of a FGFR4-amplified soft tissue tumor, failed clinical translation." (PMID 38136436, 2023). "The patient with the FANCL (head and neck cancer) received olaparib and experienced a TTF for 12 months until progress, whereas the FA patient with CDK4/CCND1 amplification deceased after 13 months, with the first treatment being olaparib (6 months) and then palbociclib (7 months)." (PMID 38136436, 2023).
Hereditary breast and ovarian cancer syndrome (1 paper, 2025). An autosomal dominant inherited syndrome caused by mutations in the BRCA1 or BRCA2 genes.
Infertility (1 paper, 2023). "Studies have shown that patients with biallelic pathogenic variants of FANCA, FANCM, FANCD1, FANCU, and patients with monoallelic pathogenic variants of FANCA, FANCD1, FANCL exhibited gonadal dysfunction and infertility." (PMID 37563658, 2023).
lung adenocarcinoma (1 paper, 2016). A carcinoma that arises from the lung and is characterized by the presence of malignant glandular epithelial cells. "In addition, polymorphisms of FANCL or FANCJ were associated with a relatively minor, but still significant, risk in male or female lung adenocarcinomas, respectively." (PMID 26842001, 2016).
myelodysplastic syndrome (1 paper, 2021). A clonal hematopoietic disorder characterized by dysplasia and ineffective hematopoiesis in one or more of the hematopoietic cell lines. "FANCL is a family member of DNA repair molecules and is frequently mutated in myelodysplastic syndrome (MDS), a pre-malignant hematopoietic disease; patients with MDS have increased risk of AML." (PMID 33592582, 2021).
premature ovarian failure (1 paper, 2025). "In women, FANCM and FANCL mutations have been associated with premature ovarian failure." (PMID 41488147, 2025).